IDH1 (isocitrate dehydrogenase (NADP(+)) 1)
Diseases named in the same sentence as IDH1 in open-access papers (continued):
Sharing a sentence is not in itself a finding about the gene and the disease.
cancer (continued). "Decreased 5-hmC levels in malignant tumors could be due to the mutation of TET genes or the mutations of isocitrate dehydrogenase 1 or 2 (IDH1/2), as mutation of IDH1/2 produces 2-hydroxyglutarate (2-HG) to inhibit the activity of TET proteins." (PMID 27911867, 2017). "Targeted therapy for IDH1 mutation has displayed great potential in cancer therapy." (PMID 28427200, 2017). "Interestingly, in vitro studies indicate that cancer cells supplement deficiency of acetyl-coA for lipid biogenesis through reductive glutamine metabolism mediated by cytoplasmic and/or mitochondrial IDH1 and IDH2, respectively." (PMID 27682873, 2017). "IDH1 may be a vulnerable requirement for particular cancer cells although other cancers bear dominant inhibitor mutations of IDH1 and presumably have other means for NADPH production." (PMID 29257069, 2017). "Recent studies on IDH1 in cancers have primarily focused on the mutations of the IDH1 gene." (PMID 27863386, 2016). "However, the hotspot R132H mutation was significantly under-represented in intrahepatic cholangiocarcinoma, suggesting a differential mutation pattern of IDH1 in different cancer types." (PMID 27469031, 2016). "One of the examples of the role of metabolism in cancer is the recently identified onco-metabolite with putative oncogenic property, 2-hydroxyglutarate (2HG), which is typically generated by mutated isocitrate dehydrogenase 1 and 2 (IDH1/2)." (PMID 26458332, 2015). "Previous genetic studies have suggested a strong correlation between IDH1 mutations and cancer." (PMID 26599207, 2015). "Previous studies have suggested that the oncometabolite D-2-HG produced by cancer-associated mutant IDH1/2 may convey oncogenic signals through altering epigenetic modifications, which leads to altered gene expression and growth promotion." (PMID 25825982, 2015). "We hypothesized that metabolic alterations induced by cancer-promoting IDH1 mutations might confer a distinct and therapeutically vulnerable “metabolic phenotype” that could be exploited to select drugs with the highest probability of clinical success." (PMID 25980580, 2015). "However, another kind of α-KG analogues, such as Octyl-2KG and related derivatives, significantly down-regulate HIF-1α in multiple cell types, including cancer cells with IDH1 or SDH mutations, by acting as a PHD cofactor to promote PHD function." (PMID 25420025, 2014). "Since the IDH mutations observed in cancer are heterozygous, it has been speculated that IDH1 and IDH2 mutants bind the remaining IDH1-WT or IDH2-WT molecules in cells and exert a dominant negative function." (PMID 21326614, 2011). "Although ivosidenib is selectively used to cure cancer patients carrying IDH1 mutations, it still exerts a suppressive function on cancer cells with normal IDH1, which implies that ivosidenib has a secondary intracellular target beyond mutant-IDH1-mediated metabolic regulation." (PMID 40299557, 2025). "Importantly, inhibitors targeting mutant IDH1 that reduce 2-HG levels show promise in preclinical and clinical settings, highlighting the therapeutic and diagnostic significance of this metabolic axis in cancer." (PMID 41154605, 2025). "However, since the enzyme kinetic results were different between G98N and R133H and the corresponding human enzymes, it seems unlikely that C. elegans would serve as a good model specifically for human cancers involving IDH1 mutations or for developing drugs that bind to IDH1." (PMID 40943163, 2025). "Additionally, these strategies may also be combined with drugs targeting cancer-specific mutations, including mutated IDH1 and IDH2, which are also known contributors of TME-induced immunosuppression." (PMID 41235226, 2025).
cancer (continued). "Most of these IDH1/2 alterations are heterozygous missense mutations that confer a neomorphic activity on the encoded enzymes, such that they convert α-ketoglutarate to (R)-2-hydroxyglutarate (2HG), identified as an oncometabolite that contributes to the malignant phenotype in these cancers." (PMID 41357766, 2025). "Thus, we can speculate that cancers with mutated IDH1 may be increasingly sensitive to depletion of the 1C pool, also." (PMID 39009411, 2024). "Indeed, more than 11,000 cancer tissues have now been analyzed by genome-wide sequencing approaches via efforts such as The Cancer Genome Atlas in the decade since our initial report of cancer-guided enzyme redesign based on IDH1 mutations." (PMID 37950065, 2023). "In addition, the binding site in arginine 132 (R132) is the most common mutation of IDH1 in cancer." (PMID 35802554, 2022). "Furthermore, patients bearing the IDH1 mutation can be benefitted from the ivosidenib or recently developed IDH1 mutant-specific peptide vaccine (IDH1-vac) and may also serve as diagnostic markers in these cancers." (PMID 35996504, 2021). "In addition, tumors baring a TET2 or IDH-1 mutation may be especially sensitive to VitC treatment, and this is also true for cancer types having high concentrations of labile iron, due to low expression of Ferroportin 1 (Fpn1) for instance." (PMID 34717701, 2021). "Furthermore, mutations in IDH1 and 2 in several cancers result in high D-2HG levels." (PMID 31221981, 2019). "However, what DNA methylation changes are common across different IDH1/2 mutated cancers remains unclear." (PMID 31727977, 2019). "The putative targets of 1p/19q codeletion, tumor suppressor genes FUBP1 and CIC, along with TERT promoter and IDH1/2 variants, generate a unique constellation of genetic aberrations which distinguish these tumors not only from other gliomas, but from most other human cancers." (PMID 31217899, 2019). "In addition, it was shown that IDH1 or IDH2 mutations could also result in the reduction of 5hmC in cancers." (PMID 26366235, 2015). "Mutated IDH1/IDH2 enzymes represent a prime example of the intersection between metabolic and epigenetic dysregulation in cancer biology." (PMID 40181550, 2026). "We characterized wild-type C. elegans IDH-1 and two mutants, G98N and R133H, that are homologous to human IDH1 mutants that are prevalent in cancer cells." (PMID 40943163, 2025). "During hypoxia, glutamine can replace glucose and form α-ketoglutarate (αKG) which will make reductive carboxylation via isocitrate dehydrogenase 1 (IDH1) to produce citrate and thus can significantly contribute to lipid biosynthesis in cancer cells." (PMID 39886047, 2025). "Ivosidenib targets the mutant metabolic enzyme IDH1 and suppresses cancer growth by normalizing the metabolic pathway." (PMID 40299557, 2025). "Here, we present 4 cases of Chilean patients with different primary malignant tumours harbouring IDH1." (PMID 40182999, 2025). "While IDH1 inhibitors are effective in other cancers, LUAD evidence remains limited; ongoing work in solid tumors supports selective, trial-based evaluation in IDH1-mutant NSCLC." (PMID 41154602, 2025). "Our findings identify key pathways driving PARPi resistance in IDH1-mutant cancers and highlight potential therapeutic strategies to overcome this resistance." (PMID 41357766, 2025). "Using this technique, they detected EGFRvIII-positive vesicles and isocitrate dehydrogenase 1 (IDH1) R132H+ cancer cell-derived EVs." (PMID 40182121, 2025). "Alterations in DNA methylation caused by mutations in IDH1 and IDH2 are common in a wide range of cancers." (PMID 40641934, 2025). "Targeting D-2-HG and its downstream effects offers a promising strategy to restore immune function in IDH1-mutant cancers." (PMID 40931345, 2025).
cancer (continued). "Subsequent mechanistic investigations revealed that ivosidenib directly targets the m6A reader protein YTHDC2 in IDH1 wild-type cancer cells, thereby impairing homologous recombination (HR) repair capacity in these BRCA-competent malignancies." (PMID 40299557, 2025). "Here, we describe loss of end protection factors 53BP1 and REV7 as a mechanism of PARPi resistance in IDH1-mutant cancers." (PMID 41357766, 2025). "ME1, G6PD, and IDH1 all play important roles in metabolic pathways that are often altered in cancer cells to support their rapid growth and proliferation." (PMID 39996805, 2025). "Knockout of these factors by CRISPR–Cas9 in IDH1-mutant cancer cells conferred robust resistance to PARPi and restored HDR capacity." (PMID 41357766, 2025). "Further exploration of the effects of individual IDH1/2 mutations on DNA methylation is arguably warranted, given that the frequencies of specific IDH1 and IDH2 driver mutations vary across other cancer types." (PMID 40545636, 2025). "Driver mutations in IDH1 and IDH2 have been implicated in several cancer types, including central chondrosarcoma, acute myeloid leukemia, and glioblastoma." (PMID 41299743, 2025). "IDH1 genotyping is frequently accomplished via IHC in other cancers such as glioma, but NGS is the preferred method in CCA as it enables simultaneous detection of actionable alterations in FGFR2, NTRK, RET, and BRAF." (PMID 39851960, 2025). "EGFR, IDH1, ARID1A, and CIC also displayed two associations each, while the remaining 68 hotspots corresponded to one gene associated with one specific cancer type." (PMID 38473427, 2024). "BAY1436032 is an oral small-molecule inhibitor of R132-mutant IDH1 that is active in preclinical models of mIDH1 cancer." (PMID 39876890, 2024). "This study demonstrated the inhibitory effect of IDH1–α-KG–HIF1a on the growth of HCC cells and evaluated the inhibitory effect of Scu, the first IDH1 small molecule agonist, which provides a reference for cancer immunotherapy involving activated IDH1." (PMID 38622131, 2024). "IDH1 and IDH2 are frequently mutated in cancer, which alters their activity so instead of generating NADPH, NADPH is consumed by the reduction of α-KG to generate 2-HG." (PMID 38674143, 2024). "The identification and subsequent analysis of IDH1/2 alterations in cancers resulted in the recognition of the IDH-TET pathway." (PMID 38686271, 2024). "IDH1 and IDH2 are frequently mutated in various types of cancer, including glioma, acute myeloid leukemia, cartilaginous tumors, etc.." (PMID 38167476, 2024). "Previous studies have demonstrated that IDH1/2 mutant cancer cells produce the tumor metabolite 2-hydroxyglutarate (2-HG) and that 2-HG-induced histone hypermethylation results in homology-directed repair defects." (PMID 38988323, 2024).
cancer (continued). "Isocitrate dehydrogenase (IDH) 1 and 2 (IDH1 and IDH2) are the most frequently mutated metabolic genes in human cancers." (PMID 38581001, 2024). "CD24 signaling, through Siglec-10 macrophages, is a target for cancer immunotherapy and is related to the mutant-IDH1-dependent chromatin state." (PMID 39619148, 2024). "Thus, IDH1 activity may play a causal role in anti‐cancer drug sensitivity and resistance." (PMID 38582508, 2024). "Association of KRAS wild-type cancers (ETV6-NTRK3, TPR-NTRK1, SCLA5-NRG1, and ATP1B1-NRG1 fusions, IDH1 R132C mutation, and mismatch repair deficiency) with early-onset of disease." (PMID 39062863, 2024). "Then, we analysed serious glycolysis‐related genes and found that IDH1 can be transcriptionally regulated by SIX4 to promote cancer cell migration." (PMID 36601689, 2023). "Ivosidenib blocks the activity of mutant IDH1, preventing cancer cells from differentiating further and from proliferating." (PMID 37631077, 2023). "Compared to the control group, the loss of skeletal muscle gastrocnemius and tibialis anterior in mice bearing IDH1-mutant cancer was 26.1% and 16.3%, respectively." (PMID 37741882, 2023). "Conversely, ctDNA from both Patients 6 and 7 had mutations in two known cancer critical genes each (BRCA1 and IDH1, and ERG and KMT2C, respectively)." (PMID 35880692, 2023). "Furthermore, we present unexpected predictive models of several DDR deficiencies; ATRX and IDH1 deficiency in cancers of the central nervous systems (CNSs), HERC2 and CDKN2A deficiency in skin, PTEN deficiency in cancers of the CNS and uterus, and SMARCA4 deficiency in cancers of unknown primary." (PMID 36883553, 2023). "Mutation analysis revealed elevated mutation rates for IDH1, HNF4A, and ATF4 in LGG, UCEC, and SKCM, as well as higher mutation rates for this ferroptosis-cancer co-associated gene." (PMID 37304867, 2023). "Next, we evaluated the IDH1 genotype-related cancer phenotypes based on the public biological information resources of the TCGA database based on cBioPortal24." (PMID 37741882, 2023). "In IDH1-R132H mutant cancer-bearing mice, cancer cachexia syndrome occurred at DPI 17, and the average lean body weight decreased by 5.4% (from 26.83 ± 1.12 g to 25.45 ± 0.98 g)." (PMID 37741882, 2023). "In the in vivo murine cancer cachexia model, mutant IDH1 in CT26 cancer cells accelerated cachexia progression and worsened overall survival." (PMID 37741882, 2023). "Elevated tissue stiffness has been reported in multiple cancers, including breast and brain, and was shown to promote cancer cell invasion by affecting pathways involving IDH1, a known cancer driver gene." (PMID 37007140, 2023). "This demonstrates that the growth of IDH1‐KO PCa cells is disrupted in an in vivo metabolic environment, correlating with a decrease in metabolic flexibility of these cancer cells." (PMID 37086156, 2023). "Virtually almost all IDH1 and IDH2 mutations are missense mutations located at R132 and R172, respectively; both isotypes are therefore promising biomarkers for cancer diagnosis and gene therapy." (PMID 36959802, 2023). "The increase of (R)-2HG in cancers with IDH1 or IDH2 mutations and metabolic preferences that distinguish cancers with unique oncogenotypes are examples of divergent pathways." (PMID 36597205, 2023).
cancer (continued). "Rarely, SB-PCCs showed high microsatellite instability, mutations in IDH1 and ERBB2 genes, or FGFR2 amplification (one case each), which are established or promising therapeutic targets in such aggressive cancers." (PMID 36812376, 2023). "IDH1 and IDH2 are the most frequently mutated metabolic genes in human cancer, and their mutations have been identified in different types of cancer, notably in gliomas, secondary glioblastomas, cartilaginous and bone tumors, and acute myeloid leukemia." (PMID 37601653, 2023). "Reports suggest that IDH1/2 mutations, inhibition of glutaminolysis, and mitochondrial cristae remodeling, and OXPHOS uncoupling increase the anti-cancer efficacy of ABT-199." (PMID 37242775, 2023). "Genetic and pharmacological inhibition of IDH1 was then combined with extracellular flux analyses and gas chromatography–mass spectrometry for metabolomic analyses and cancer cell proliferation in vitro and in vivo." (PMID 37086156, 2023). "Well‐known cancer critical genes like BRCA1, IDH1, ERG, KMT2C, MSH6 and PALB2 were among the mutated genes in the metastatic samples." (PMID 35880692, 2023). "This uncovers a new axis for immunotherapeutic improvement in GBM and other cancers, reveals novel physiological and molecular functions of IDH1, and hints at an unexpectedly direct link between lytic T cell function and metabolic activity in target cells." (PMID 37161052, 2023). "IDH1/2mt cancers are sensitive to BCL2 inhibition because D-2-HG accumulation induces BCL2 dependence via inhibition of cytochrome c oxidase, also known as complex IV of the electron transport chain." (PMID 34967233, 2022). "Recent studies have shown successful treatments using neoantigen-based shared cancer vaccines in some types of cancers such as IDH1 R132H for glioblastoma and KRAS G12D for colon cancer." (PMID 36298462, 2022). "We further used the CGGA-LGG database to compare the difference in FCGR3A mRNA expression in groups divided by age, gender, cancer type, WHO grade, 1p19q codel, IDH1-mutation, MGMT methylated, radiotherapy treatment, and chemotherapy treatment." (PMID 39280892, 2022). "Noteworthily, we find that IDH1 and SETD2 mutations are potential shared drivers across nine CIMP-positive cancer types, albeit in sometimes rare subpopulations (such as in LUAD)." (PMID 35134107, 2022). "The presence of these specific conditions render cancer cells vulnerable to allosteric IDH1 inhibition." (PMID 36153582, 2022). "For example, researchers found causation between mutations in IDH1, IDH2 and TET2—which negatively affect DNA hydroxymethylation rates—and CIMP in leukemia, gliomas and several other cancer types." (PMID 35134107, 2022). "Fourth, and most importantly, this study reveals that allosteric IDH1 inhibitors, which were designed to selectively target mIDH1, are even likely to be active against cancers that lack the mutant protein." (PMID 35681100, 2022). "We found that hyperthermia in combination with radiation or cisplatin induces an increase in double-strand breaks and cell death, up to 10-fold in IDH1MUT cancer cells compared to IDH1 wild-type cells." (PMID 36551714, 2022). "In fact, beneath certain metabolic circumstances, such as hypoxia, cancer cells preferentially employ glutamine-derived chemicals in lipogenesis over the preferred IDH1 pathway-producing molecule." (PMID 35912242, 2022). "Considering that Dasatinib and PARP1 inhibitors have been reported in IDH1/2 mutant ICC or other cancers 54-56, we tested the effect of JQ1 and Vorinostat on clone formation ability in four ICC cell lines." (PMID 34987644, 2022). "Point mutations in the isocitrate dehydrogenases IDH1 and IDH2 have been confirmed as oncogenic drivers in only 0.9%–3% of all cancers." (PMID 35732120, 2022). "While OXPHOS dysfunction has been shown to induce IDH1/2-mediated reductive carboxylation in certain cancer cells, the TCA cycle function is intact in this context." (PMID 35740646, 2022).